BMAL1 (basic helix-loop-helix ARNT like 1)
Diseases named in the same sentence as BMAL1 in open-access papers (continued):
Sharing a sentence is not in itself a finding about the gene and the disease.
adrenocortical carcinoma (2 papers, 2023 to 2025). "BMAL1 depletion enhances the sensitivity of adrenocortical carcinoma cells to DNA damage-based therapies both in vitro and in vivo, implicating BMAL1 as a potential target in cancer therapeutics." (PMID 40243466, 2025). "Accordingly, depletion of BMAL1 significantly enhances the sensitivity of adrenocortical carcinoma (ACC) to DNA damage-based therapy in vitro and in vivo." (PMID 36725890, 2023). "Furthermore, SW-13 cell, the adrenocortical carcinoma (ACC), depleted BMAL1 increases the sensitivity to Zeocin, and that overexpression of BMAL1-WT, but not BMAL1-S183A, increases the resistance of SW-13 cell to Zeocin." (PMID 36725890, 2023).
age (2 papers, 2018 to 2021). A temporal measurement of the time period elapsed since an identifiable point in the life cycle of an organism. "Our findings are consistent with early work, demonstrating that mice deficient in circadian clock proteins, such as BMAL1 and CLOCK, display age-related cataract." (PMID 34127677, 2021).
aging (2 papers, 2022). A developmental process that is a deterioration and loss of function over time. "Hence, exercise, TRF, adiponectin, and supplementation with NMN and NR might also be promising treatment strategies for aging‐related diseases that are dependent on the modulation of Bmal1." (PMID 36056774, 2022).
alcohol (2 papers, 2015 to 2022).
allergic rhinitis (2 papers, 2018 to 2023). Inflammation of the nasal mucous membranes caused by an IgE-mediated response to external allergens. "CC1, characterized by a high expression of PER genes and low expression of CLOCK and BMAL1, had the highest prevalence of comorbid allergic rhinitis and atopic dermatitis, caused by general activation of immune-related signaling pathways." (PMID 37108640, 2023). "CC2, characterized by low expression of PER genes and BMAL1, had the youngest median age and a low prevalence of allergic rhinitis, a condition that is associated with decreased activation of the FcεRI signaling pathway." (PMID 37108640, 2023). "The present study investigates the expression level and distribution pattern of PER1, PER2, CLOCK, and BMAL1 genes in nasal mucosa of healthy controls, allergic rhinitis patients, and normal rats." (PMID 29534090, 2018).
Allergy (2 papers, 2018 to 2025). An allergy is an immune response or reaction to substances that are usually not harmful. "The circadian rhythm of this type I allergy synchronizes with that of Bmal1 and Clock, and when the expression of Bmal1 and Clock is high, type 1 allergy becomes severe." (PMID 30069250, 2018). "Altered protein levels of CLOCK, BMAL1, REV-ERBs, and RORs in eosinophils from asthmatics reflected the disease severity and allergy status of the patients." (PMID 40131242, 2025).
autism spectrum disorder (2 papers, 2017 to 2025). A spectrum of developmental disorders that includes autism, and Asperger syndrome. "Here, we identified rare variants in BMAL1 in 10 individuals with a neurodevelopmental phenotype characterized by developmental delay and autism spectrum disorder." (PMID 40720646, 2025).
Autoimmunity (2 papers, 2017 to 2024). The occurrence of an immune reaction against the organism's own cells or tissues. "We also found an association between BMAL1 expression in circulating neutrophils and clinical/serological parameters of disease activity in human SLE, supporting a role for circadian rhythm disturbances in autoimmunity development and perpetuation." (PMID 39664388, 2024). "Here the authors show that the master circadian gene, Bmal1, is essential for modulating the homeostasis of myeloid cells to control pro-inflammatory IL-17+/IFN-γ+ T cells in autoimmunity." (PMID 29234010, 2017). "However, EAE was attenuated in mice which had T cells lacking Bmal1, indicating that Bmal1 is specifically protective in the myeloid lineage for autoimmunity." (PMID 29234010, 2017).
brain injuries (2 papers, 2017 to 2020). "Similarly, moderate TBI dysregulates expression of Bmal1 and Cry, and concurrent circadian locomotor activity, suggesting that altered clock gene expression may underlie the sleep disturbances associated with many brain injuries." (PMID 29108016, 2017).
brain tumor (2 papers, 2021 to 2025). "Based on these results, BMAL1 may plays an important role in brain tumor microangiogenesis and peritumor edema." (PMID 34815366, 2021).
Cachexia (2 papers, 2014 to 2024). Severe weight loss, wasting of muscle, loss of appetite, and general debility related to a chronic disease. "Notably, altering the light–dark cycle and lentiviral inhibition of Bmal1 exacerbate adipocyte size reduction, lipid content decrease in fat droplets, and worsen ectopic lipid deposition during cachexia progression in the hypermetabolic state." (PMID 38584196, 2024). "We observed reduced amplitudes in the mRNA expression of Reverbα Per2, Pparγ C/ebpα, and associated genes (Fas, Lpl, Scd1, Dgat2) and a parallel increase in Bmal1, Cry1, Pbe and Tfam indicating alterations in the core clock regulation and lipid homeostasis during cachexia." (PMID 24667661, 2014).
clear cell renal cell carcinoma (2 papers, 2025). "Here, the authors show that BMAL1 can form a heterodimer with HIF2α in clear cell renal cell carcinoma, contributing to tumor progression and response to HIF2α antagonist drugs." (PMID 40595592, 2025).
colon adenocarcinoma (2 papers, 2019 to 2021). "To examine the role of BMAL1 in small intestinal glucose absorption, we used differentiated human colon adenocarcinoma cells (Caco-2 cells)." (PMID 31216190, 2019). "Compared to normal skin, patients with skin cutaneous melanoma (SKCM) present significant down-regulation in the expression of BMAL1, CRY1, CRY2, PER1, PER2, and PER3, and higher expression of CLOCK, a similar pattern was also observed in patients with colon adenocarcinoma (COAD)." (PMID 34966277, 2021).
delirium (2 papers, 2022 to 2025). A disorder characterized by confusion; inattentiveness; disorientation; illusions; hallucinations; agitation; and in some instances autonomic nervous system overactivity. "In a different paradigm, wild‐type mice were gavaged with SR8278 for 7 days to specifically increase intestinal BMAL1 expression, and then delirium induction was initiated." (PMID 40539410, 2025). "Delirium resulted in overall disruption of core clock genes in mouse hippocampus, including E4bp4, Bmal1, Rev‐erbα, Cry1, and Per2." (PMID 35713240, 2022). "In sharp contrast, the effects of SR8278 on delirium development were lost in Bmal1‐iKO mice." (PMID 40539410, 2025). "In addition, we observed disrupted rhythms in E4BP4, BMAL1, and REV‐ERBα in the whole blood of patients with delirium." (PMID 35713240, 2022).
diffuse large B-cell lymphoma (2 papers, 2016 to 2017). "Bmal1 is transcriptionally silenced by promoter CpG island hypermethylation in hematologic malignancies, such as diffuse large B-cell lymphoma and acute lymphocytic and myeloid leukemia." (PMID 27602774, 2016). "Diffuse large B-cell lymphoma (DLBCL), ALL, and AML display promoter hypermethylation at the BMAL1 gene." (PMID 28674522, 2017).
Duchenne muscular dystrophy (2 papers, 2024 to 2025). Duchenne muscular dystrophy (DMD) is a neuromuscular disease characterized by rapidly progressive muscle weakness and wasting due to degeneration of skeletal, smooth and cardiac muscle. "Furthermore, using genetic approaches targeting Bmal1 in the Duchenne muscular dystrophy (DMDmdx) mouse model, it was shown that a loss of Bmal1 significantly accelerated dystrophic disease progression due to impaired myogenic progenitor proliferation." (PMID 41009036, 2025).
esophageal squamous cell carcinoma (2 papers, 2024 to 2025). Esophageal squamous cell carcinoma (ESCC) is a type of esophageal carcinoma (EC) that can affect any part of the esophagus, but is usually located in the upper or middle third. "Concerning the role of DUSP1 in oesophageal squamous cell carcinoma (ESCC), it was demonstrated that overexpression of the circadian transcription factor ARNTL (also known as BMAL1) upregulates the expression of DUSP1 by inducing its transcription." (PMID 40943262, 2025).
glaucoma (2 papers, 2025 to 2026). Increased pressure in the eyeball due to obstruction of the outflow of aqueous humor. "Glaucoma-induced phase shifts and amplitude alterations in the rhythmic expression of Per1, Per2, Nr1d1, and Bmal1 in the pituitary and adrenal gland, resulted in a temporal misalignment between the pituitary and adrenal rhythms." (PMID 42029480, 2026). "Disruption of the circadian rhythm has been demonstrated to cause alterations in the fate of Bmal1, which is associated with an elevated risk of retinal diseases, such as DR, AMD, and glaucoma." (PMID 41243864, 2025). "Although direct evidence is still limited, the regulatory roles of Bmal1 in IOP, oxidative stress, and neuroinflammation highlight its potential as a promising therapeutic target for glaucoma." (PMID 41243864, 2025).
head and neck cancer (2 papers, 2016 to 2019). A primary or metastatic malignant neoplasm affecting the head and neck. "It is unclear whether compromised PTEN function that leads to accumulation of BMAL1 is specific to head and neck cancer or is a normal regulatory mechanism found in epithelial cells." (PMID 27285754, 2016). "Notably, inhibition of mTOR signaling (mTORC1 and mTORC2) results in restoration of normal BMAL1 levels in the epidermis in vivo, and also in head and neck cancer cells." (PMID 27285754, 2016).
hyperandrogenism (2 papers, 2020 to 2025). Excessive secretion of androgens from the adrenal glands or gonads. "Studies have also revealed that dysregulation of the expression of some essential clock genes, such as BMAL1, is closely associated with hyperandrogenism." (PMID 40838208, 2025). "CYP19A1 has also been identified as an immediate objective of BMAL1 in PBMCs, and low expression of BMAL1 increases the activity of 5a-reductase, exacerbating hyperandrogenism." (PMID 40838208, 2025). "Perturbations in core clock genes, such as Brain and Muscle ARNT-like protein-1 (BMAL1), have been implicated in PCOS pathogenesis, particularly hyperandrogenism." (PMID 40838208, 2025).
infarction (2 papers, 2023 to 2024). A localised pathological necrosis of tissue resulting from obstruction of the blood supply usually by a thrombus, an embolus, or vascular torsion. "Together, these data confirm that the Sm-Bmal1 KO vascular phenotype exerts beneficial effects on cardiac performance and remodelling following infarction." (PMID 36418171, 2023). "Thus, neutrophil-specific deletion of Bmal1 results in defective aging, contributing to reduced infarction post-MI86." (PMID 38464103, 2024).
insulinoma (2 papers, 2020 to 2023). "To address this, we investigated the consequences of Bmal1 inhibition in an insulinoma cell line (INS-1) by using small interfering RNA (siRNA)." (PMID 32964049, 2020). "Circadian expression of clock genes (Clock, Bmal1, Per1,2,3, and Cry1,2) in pancreatic islets and INS1 rat insulinoma cells may indicate that circadian rhythms are generated within the b-cells." (PMID 36768693, 2023).
intervertebral disc degeneration (2 papers, 2022 to 2024). "HSA-let-7f-1–3p, which is a micro RNA targeting the circadian gene Bmal1, can mediate the process of intervertebral disc degeneration by regulating autophagy." (PMID 38895112, 2024). "Specific deletion of Bmal1 in astrocytes affects autophagy and protein degradation kinetics, and Bmal1 can mediate the process of intervertebral disc degeneration by regulating autophagy." (PMID 38895112, 2024). "Also, as a central component of the molecular basis of the biological clock, Bmal1 attenuates apoptosis and modulates extracellular matrix metabolism by activating autophagy in intervertebral disc degeneration." (PMID 38895112, 2024).
intestinal tumor (2 papers, 2022 to 2024). "Together, these data indicate that concurrent Bmal1 and Apc loss significantly rewires global gene expression programs involved in driving intestinal tumor progression." (PMID 35947664, 2022). "However, loss of Bmal1 was found to increase the intestinal tumor initiation by promoting the expression and activity of YAP, which was in contrary to our results." (PMID 38150082, 2024).
Kyphoscoliosis (2 papers, 2024 to 2025). An abnormal curvature of the spine in both a coronal (lateral) and sagittal (back-to-front) plane. "A previous study reported that 6‐month‐old mice with an osteoblast‐specific BMAL1 deletion developed spinal kyphoscoliosis deformities." (PMID 39045886, 2024).
limb ischemia (2 papers, 2021 to 2022). A ischemia that involves the limb. "In this study, we found that circadian gene Bmal1 disruption aggravates critical limb ischemia by promoting lipid uptake and inflammation and impairing angiogenesis." (PMID 34447794, 2021). "In addition, BMAL1 plays an important role in critical limb ischemia by activating IL-10, which transcriptionally suppresses inflammation and promotes angiogenesis via the transcriptional regulation of vascular endothelial growth factor expression." (PMID 36505412, 2022).
Myocardial fibrosis (2 papers, 2022 to 2026). "Collectively, our findings reveal BMAL1 as a critical negative regulator of post-MI myocardial fibrosis by inhibiting the TGF-β1/SMAD3 pathway mediated by SMAD7." (PMID 41909150, 2026). "Altogether, these results suggested that BMAL1 overexpression inhibited the inflammatory reaction and prevented myocardial fibrosis induced by Ang II." (PMID 35996077, 2022).
opioid use disorder (2 papers, 2023 to 2024). A substance-related disorder that involves the recurring use of opioids despite negative consequences. "Similarly, NR1D2, BMAL1, and CSNK1D rhythms were disrupted in opioid use disorder (OUD) and AUD patients compared to controls." (PMID 39766481, 2024).
papillary thyroid carcinoma (2 papers, 2015 to 2022). "We previously reported an upregulation of the clock transcript BMAL1, correlating with TIMP1 expression in fresh-frozen samples from papillary thyroid carcinoma (PTC)." (PMID 25868389, 2015).
pneumonia (2 papers, 2020 to 2024). An acute, acute and chronic, or chronic inflammation focally or diffusely affecting the lung parenchyma, caused by an infection in one or both of the lungs (by bacteria, viruses, fungi, or mycoplasma.). "BMAL1 deficiency in macrophages protects mice from pneumonia, exhibiting increased macrophage motility and bacterial clearance, resulting in a lower bacterial burden in blood." (PMID 38938563, 2024).
psoriasis (2 papers, 2022 to 2024). An autoimmune condition characterized by red, well-delineated plaques with silvery scales that are usually on the extensor surfaces and scalp. "A previous report showed that Bmal1 germline KO mice displayed worsening of IMQ-induced psoriasis and systemic type I IFN responses." (PMID 39664388, 2024).
psychosis (2 papers, 2019). "Taken together, the behavioral and electrophysiological results indicated that BMAL1-KO monkeys represent a potential non-human primate model for studying the causal link between circadian disorders and psychosis." (PMID 34691834, 2019).
renal carcinoma (2 papers, 2014 to 2025). A carcinoma arising from the epithelium of the renal parenchyma or the renal pelvis. "Considering the results that the Per2 circadian rhythm was shown only in Caki-2 cells, which contained BMAL1, CLOCK, and HIF1α protein, it is possible that HIF1α is related to the Per2 circadian rhythm in renal cancer cell lines." (PMID 25333958, 2014). "This suggested that both BMAL1/CLOCK and HIF1α may be related to the circadian expression of Per2 in renal cancer cell lines." (PMID 25333958, 2014). "Furthermore, we find that BMAL1 protein is present in a greater proportion of nuclei, and therefore likely to be more active, in ccRCC tumors compared to non-tumor kidney samples and compared to other types of renal cancer." (PMID 40595592, 2025).
skin tumors (2 papers, 2016 to 2021). "In fact, Bmal1−/− mice have been shown to be less likely to develop skin tumors throughout initial, middle, and late stages of carcinogenesis." (PMID 27128901, 2016). "Moreover, Bmal1 KO reduced the development of murine skin tumors by reducing tumor-initiating cells and enhancing the expression of tumor suppressor genes." (PMID 33816508, 2021).
Sleep disturbance (2 papers, 2023 to 2025). An abnormal pattern in the quality, quantity, or characteristics of sleep. "We identified 10 individuals with neurodevelopmental features, sleep dysfunction, and musculoskeletal symptoms associated with ultrarare variants in BMAL1." (PMID 40720646, 2025).
spinal cord injury (2 papers, 2024 to 2025). Penetrating and non-penetrating injuries to the spinal cord resulting from traumatic external forces (e.g., WOUNDS, GUNSHOT; WHIPLASH INJURIES; etc.). "The impact of Bmal1 on the motor recovery of mice was assessed by monitoring Basso Mouse Scale (BMS) scores at 3, 7, 14, 21, and 28 days following spinal cord injury (SCI)." (PMID 39648661, 2024).
status epilepticus (2 papers, 2018 to 2021). Status epilepticus is defined as a continuous seizure lasting more than 30 min, or two or more seizures without full recovery of consciousness between any of them. "In line with the human data, we observed increased Rev-erbα expression in both hippocampus and cortex in kainic acid (KA)-treated mice (a model of status epilepticus) that was accompanied by reductions in Bmal1, Clock, E4bp4, and Dbp mRNAs." (PMID 33619249, 2021). "In this study, we systematically evaluated the temporal expression of seven core circadian transcripts (Bmal1, Clock, Cry1, Cry2, Per1, Per2, and Per3) and the spontaneous locomotor activity (SLA) in post-status epilepticus (SE) model of mTLE." (PMID 30116220, 2018).
tendinopathy (2 papers, 2025). "•Disruption of Bmal1-Nrf2 axis exacerbates AT inflammation; Boosting Bmal1 mitigates tendinopathy." (PMID 39442875, 2025). "Enhancing Bmal1 expression mitigated tendinopathy and increased AT relief." (PMID 41009036, 2025). "Additionally, we developed an injectable biomaterial based on Nb2C@CeO2 with Schottky heterojunctions capable of regulating the expression of Bmal1 to modulate circadian rhythms and verified their effectiveness in treating tendinopathy." (PMID 39442875, 2025).
thyroid nodule (2 papers, 2015 to 2020). A small circumscribed mass in the THYROID GLAND that can be of neoplastic growth or non-neoplastic abnormality. "Furthermore, variants of various clock genes (PER2–3, CRYs, BMAL1, REV-ERBs and RORs) and strong changes in their expression profile have been found on thyroid nodule malignant transformation and have been proposed as potential biomarkers for thyroid nodule pre-operative diagnostics." (PMID 33114365, 2020).
tongue cancer (2 papers, 2016 to 2026). A malignant neoplasm affecting the tongue. "The core clock factor BMAL1 influences drug resistance in multiple cancers, enhancing paclitaxel sensitivity in tongue carcinoma." (PMID 41480765, 2026). "Considering this, cultured tongue cancer cells and control cells were synchronized and used to confirm the relationship between BMAL1/CLOCK and PFKFB3." (PMID 27079271, 2016). "Of interest, the expression of key clock genes was either down-regulated, e.g., BMAL1, CLOCK, PER1, PER2, and PER3, or up-regulated, e.g. CYR1 and CRY2, in tongue cancer samples in relative to that in normal control samples." (PMID 27079271, 2016). "However, the down-regulation of BMAL1 and CLOCK expression and the up-regulation of PFKFB3 expression in tongue cancer samples do not necessarily imply that BMAL1 and/or CLOCK down-regulation leads to increased PFKFB3 expression." (PMID 27079271, 2016).